SSUH2 (ssu-2 homolog)
Description:
Plays a role in odontogenesis.
Synonyms: C3orf32; FLS485; ssu-2; DTDP1C
Tractability: No criterion of Open Targets' tractability assessment is met for any kind of drug.
Gene: Protein-coding gene on chromosome 3 (8,619,386 to 8,745,040, reverse strand). Ensembl gene ENSG00000125046.
Subcellular location: Cytoplasm; Nucleus
Gene Ontology:
Molecular function: heat shock protein binding
Biological process: odontogenesis
Cellular component: cytoplasm; nucleus
Genetic constraint (gnomAD): Loss-of-function variants: 38 observed, 43.69 expected, observed/expected ratio (o/e) 0.87, 90% interval 0.67 to 1.14. The upper end of that interval is the gene's LOEUF score, 1.14, which puts it in group 4 of 6, group 1 being the genes least tolerant of losing a copy. Missense variants: 474 observed, 427.64 expected, observed/expected ratio (o/e) 1.11, 90% interval 1.03 to 1.2. Synonymous variants: 194 observed, 167.61 expected, observed/expected ratio (o/e) 1.16, 90% interval 1.03 to 1.3.
Homologues: Orthologues: chimpanzee SSUH2 (99% identical), macaque SSUH2 (97% identical), pig SSUH2 (89% identical), dog SSUH2 (88% identical), mouse Ssu2 (83% identical), rat Ssuh2 (80% identical), guinea pig SSUH2 (65% identical), rabbit SSUH2 (54% identical), zebrafish ssuh2.1 (14% identical).
Diseases named in the same sentence as SSUH2 in open-access papers:
SSUH2 is named in the same sentence as 4 diseases in open-access papers, as found by Europe PMC text mining. Sharing a sentence is not in itself a finding about the gene and the disease. The quoted sentences say what the papers report.
Hypertension (1 paper, 2023). The presence of chronic increased pressure in the systemic arterial system. "Furthermore, PIK3C2G, FIBIN, CHRNA1, NPNT, MEOX1, and POU2F2 linked obesity and lung cancer, while PTPRQ, SSUH2, CILP2, CDH2, ABCA12, CPXM1, and L1CAM linked hypertension and lung cancer." (PMID 36685671, 2023).
SSUH2 also shares sentences with these, for which no sentence is quoted: celiac disease (1 paper); lung carcinoma (1); Obesity (1).